CD4 (CD4 molecule)
Diseases named in the same sentence as CD4 in open-access papers (continued):
Sharing a sentence is not in itself a finding about the gene and the disease.
type 1 diabetes (continued). "Our work clearly revealed that children with type 1 diabetes are characterized by lower percentage and absolute number of CD4+CD25high regulatory T cells as compared with age-matched healthy individuals." (PMID 21584225, 2011). "Children with type 1 diabetes were characterized by lower number and percentage of the CD4+CD25high T cells (P = .00084, P = .00026), lower number and percentage of the CD4+CD25highCD62Lhigh (P = .00012, P = .0000) than their healthy counterparts." (PMID 21584225, 2011). "In the nonobese diabetic (NOD) mouse, the most common animal model of human type 1 diabetes, it is observed an autoimmune destruction of pancreatic β cells, mediated by both CD4+ and CD8+ T cells." (PMID 22144985, 2011). "CD4 to CD8 cell surface ratios have been shown to be heritable in a large cohort of Brisbane adolescent twins, and to be associated with Type 1 Diabetes as well as control of HIV infection." (PMID 21217831, 2010). "Intranasal administration of islet auto-antigens in mice also elicited antigen-specific CD4+CD25+ Treg cells able to prevent development of type 1 diabetes." (PMID 19754943, 2009). "In experimental models, Type 1 diabetes T1D can be prevented by adoptive transfer of CD4+CD25+ FoxP3+ suppressor or regulatory T cells." (PMID 17206281, 2007). "Altered PD-1/PD-L1 interactions are involved in type 1 diabetes pathogenesis: while PD-L1 expression on β-cells can be increased due to upregulation, lower PD-1 expression on CD4+ T lymphocytes increases islet infiltration with autoreactive CD4+ and CD8+ lymphocytes." (PMID 40729244, 2025). "In this study, we utilized scRNA-seq to investigate gene expression changes in CD4+ T cells early during the development of type 1 diabetes analysing longitudinal samples from a prospective cohort of early progressors who developed the disease before the age of 5 years." (PMID 41462339, 2025). "Type 1 diabetes (T1D) is an autoimmune disease that results from the destruction of insulin-producing beta cells in the pancreas by infiltrating immune cells, including CD4+ and CD8+ T cells and macrophages." (PMID 38490439, 2024). "Interestingly, in a mouse model of type 1 diabetes, mice fed with acetate-yielding chow exhibited a reduction in autoreactive T cells (both CD4+ and CD8+) and ultimately reduced the incidence of the disease." (PMID 37485352, 2023). "CD4+ T cell stimulation with Nt-INSP-4, oxPTM-INSP-6 and oxPTM-INSP-3 was associated with antibody reactivity to oxPTM-INS in 8/18 (44.4%), 8/18 (44.4%) and 7/18 (38.9%) participants with type 1 diabetes." (PMID 36207582, 2023). "In the early stage of type 1 diabetes, antigen-presenting cells (APCs) present autoantigens such as preproinsulin (PPI), insulinoma-associated antigen 2 (I-A2), GAD, and zinc transporter (ZnT8) to CD4+ T cells." (PMID 35242127, 2022). "Since we noted that astilbin could reduce IFN-γ and TNF-α in CD4+T cells, we then analyzed whether astilbin could repress the onset of type 1 diabetes in NOD mice by regulating CD4+T cells." (PMID 35652039, 2022). "We conclude that activated memory CD4+ Tregs from slow progressors are expanded and enriched for GITR expression, highlighting the need for further study of Treg heterogeneity in individuals at risk of developing type 1 diabetes." (PMID 34709423, 2022). "Tocilizumab reduced T cell IL-6R signaling but did not modulate CD4+ T cell phenotypes or slow the loss of residual β cell function in newly diagnosed individuals with type 1 diabetes." (PMID 35563276, 2022). "To conclude, unsupervised clustering, validated by a highly consistent semi-automated gating analysis, shows that the specific circulating immune profile of newly diagnosed type 1 diabetes is characterized by increased frequency of N CD4 T cells and pDCs, and decreased CD56bright NK cells." (PMID 36389771, 2022).
type 1 diabetes (continued). "Therefore, Il-10 deficiency in BDC2.5+ NOD mice significantly affects the activation, proliferation, and function of CD4+ T cells, and thus contributes to the development of type 1 diabetes." (PMID 34394099, 2021). "Tocilizumab reduced T cell IL-6R signaling but did not modulate CD4+ T cell phenotypes or slow loss of residual β cell function in newly diagnosed individuals with type 1 diabetes." (PMID 34747368, 2021). "Furthermore, CD4 T follicular helper (Tfh) cells in patients with type 1 diabetes have increased IL-21 production, compared to healthy donors." (PMID 34616408, 2021). "For example, CD4+ T cells exert a significant role in pathogenesis of Type 1 Diabetes (T1D)." (PMID 34899740, 2021). "In Type 1 Diabetes (T1D), CD4+ T cells initiate autoimmune attack of pancreatic islet β cells." (PMID 34163475, 2021). "Interestingly, type 1 diabetes credible sets were strongly enriched in immune cell enhancers, particularly enhancers active in CD4+ and CD8+ T cells." (PMID 32477401, 2020). "We sought to determine whether the protection from type 1 diabetes seen in the global CD226 KO mouse could be attributed to the altered function of CD4+ or CD8+ T cells." (PMID 33013915, 2020). "Furthermore, consistent with immune dysregulation in type 1 diabetes, CD4+ Teff activated PD1high were decreased in type 1 diabetes patients at day 6 of anti-CD3/CD28 stimulation upon Pep3 pretreatment." (PMID 31995625, 2020). "Previous reports have indicated that antigen-specific CD4+ T cells may be found in the peripheral blood of both healthy people and those with type 1 diabetes." (PMID 32157332, 2020). "We found that the insulin-treated persons with type 1 diabetes displayed a Th2-biased immune phenotype with a high proportion of effector CD4+ T cells and CD19+ B cells, and a downregulation of Th1 serum cytokines, irrespective of their capacity for glycemic control." (PMID 32626786, 2020). "Moreover, higher frequencies of CD4+ T cells with a central memory phenotype (CD27intCD127+CD95int) were detected in individuals with newly diagnosed type 1 diabetes (mean percentage of total CD4+ T cells was 7.78%, p < 0.05) compared with healthy donors." (PMID 32157332, 2020). "It is likely that CD226 drives pathogenicity in both cell types, and further interrogation of CD4+ T cell phenotype in the CD226 KO mouse may uncover mechanisms by which CD226 expression on CD4+ T cells contributes to type 1 diabetes." (PMID 33013915, 2020). "Of these, 12 out of 20 were found in naive and central memory cells, six out of 20 were exclusively in naive cells and two out of 20 were exclusively in the central memory CD4 T cell populations in both participants with type 1 diabetes and healthy individuals." (PMID 32248243, 2020). "In the current study, we demonstrate that circulating CXCR5−PD-1hi memory CD4+ T cells display a B cell helper phenotype ex vivo and appear to be expanded in children with newly diagnosed type 1 diabetes as well as in autoantibody-positive children who later progressed to clinical disease." (PMID 31270583, 2019). "The frequency of CXCR5−PD-1hi T cells in peripheral blood is low, on average around 1% of memory CD4+ T cells, and the increase in circulating Tph cell frequencies in children with type 1 diabetes and AAb+ children and healthy control children is modest at best." (PMID 31270583, 2019). "In mice, conditional deletion of Foxp3 in CD4+ T cells leads to fatally lymphoproliferative autoimmunity, which includes high IgE levels, enteropathy, type 1 diabetes and failure to thrive, while ectopic expression of Foxp3 can re-program conventional CD4+ T cells as anti-inflammatory Treg cells." (PMID 31681337, 2019). "However, when STZ is administered at low doses during five consecutive days, it induces mild type 1 diabetes, through a T-lymphocyte-dependent process, an autoimmune destruction of pancreatic β cells mediated by both CD4+ and CD8+ T cells." (PMID 29317893, 2017).
type 1 diabetes (continued). "CD4 T cells expressing CD40 (Th40) are pathogenic in type I diabetes but have not been evaluated in EAE." (PMID 28192476, 2017). "As type 1 diabetes is an autoimmune, inflammatory disease, where Treg defects have been described, we aimed to analyze the in vitro influence of recombinant IL-33 on quantitative properties of regulatory CD4+CD25highFOXP3+ T cells." (PMID 27761063, 2016). "IL-33 could induce Treg cells in patients with type 1 diabetes; however, more studies including qualitative characterization of IL-33 treated CD4+CD25highFOXP3+ on a larger group of patients need to be done." (PMID 27761063, 2016). "We therefore explored whether the combination of ATS treatment with CD4+ T cell converted DN T cells could reverse new onset type 1 diabetes in NOD mice." (PMID 26911290, 2016). "Moreover, in NOD mice, Gal-9 showed a therapeutic potential in type 1 diabetes,as it was capable of inducing apoptosis of CD4+ Tim-3+ Th1 cells." (PMID 25880730, 2015). "Indeed, numerous reports have shown that MDSC promote the development and homeostasis of Tregs over CD4+ T effector cells, notably in the context of type 1 diabetes." (PMID 24927018, 2014). "Within the CD4+CD25highCD127low T cell population, 1,25(OH)2D3 or TX527 increased the expression of the Treg-associated molecule cytotoxic T lymphocyte antigen 4 (CTLA-4, CD152) in T cells of control subjects and patients with type 1 diabetes." (PMID 25279717, 2014). "The higher frequencies of GAD65250–266-specific total and memory CD4+ T cells in subjects with type 1 diabetes suggest that quantity and phenotypic changes for self-reactive T cells might be an indicator for loss of tolerance." (PMID 25405480, 2014). "While a recent study showed ZnT8-specific IFN-γ-producing CD4+ T cells were present in healthy adults at a lower frequency than in type 1 diabetes patients, we were intrigued by the fact that ZnT8 peptides induced strong IP-10 secretion in 5 out of 10 healthy donors." (PMID 23390544, 2013). "The analysis of Tregs in peripheral blood of DM1 patients and healthy individuals revealed lower percentage and the absolute number of CD4+Foxp3+ regulatory T cells in diabetic type 1 patients in comparison to healthy individuals from the control group (P = 0.0004 and P = 0.0003, resp)." (PMID 23533301, 2013). "Islet autoantigen-specific CD4+ T cells play a pivotal role in type 1 diabetes." (PMID 23418596, 2013). "However, when STZ is administered at low doses during 5 consecutive days, it induces mild type 1 diabetes, through a T-lymphocyte-dependent process, an autoimmune destruction of pancreatic β cells mediated by both CD4+ and CD8+ T cells." (PMID 23565805, 2013). "We next applied our integrated assay to determine whether the type of ZnT8-specific CD4+ T cells is different between Type 1 diabetes patients and age/gender/HLA-matched healthy adults." (PMID 23390544, 2013). "However, streptozotocin, administered at low doses during 5 consecutive days, induces mild type 1 diabetes, following a T-lymphocyte-dependent process, an autoimmune destruction of pancreatic β cells, mediated by both CD4+ and CD8+ T cells." (PMID 22144985, 2011). "A recent article, studied the effects of altering specific regions of a type 1 diabetes (T1D) autoantigen, the X-idiotype a 16 residues long peptide that is known to activate CD4+ T cells more effectively than insulin, could aid in designing a vaccine to treat this disease." (PMID 39975445, 2025). "In addition, CB1R may be responsible for CD4+ T cell polarisation, and changes in circulating CD4+ T cells have been described in individuals at the onset of type 1 diabetes." (PMID 38864887, 2024). "Thus, the decreased levels of TIGIT in cytotoxic CD57+CD4+ T cells of children who later develop type 1 diabetes may play a role in the disease progression." (PMID 38714671, 2024).
type 1 diabetes (continued). "Thus, the lower level of TIGIT expression in CD57+CD4+ T cells of children developing type 1 diabetes may contribute to the disease progression." (PMID 38714671, 2024). "Conventional immunosuppressive functions of CD4+Foxp3+ regulatory T cells (Tregs) in type 1 diabetes (T1D) pathogenesis have been well described, but whether Tregs have additional non-immunological functions supporting tissue homeostasis in pancreatic islets is unknown." (PMID 37577652, 2023). "However, N CD4 T cell frequency was found unaltered in pre-symptomatic stages of type 1 diabetes, suggesting that the role of these cells may be crucial in a later phase of the autoimmune response." (PMID 36389771, 2022). "Therefore, vitamin D could downregulate the expression of CatG to inhibit CD4+ T cell activation and prevent the destruction of islet β cells by immune cells and is expected to play a therapeutic role as an immunomodulator in type 1 diabetes." (PMID 36090587, 2022). "The CGRP-specific CD4 T cells could be a unique marker for type 1 diabetes." (PMID 36189304, 2022). "CD4+ T cells play an important role in the occurrence and development of T1DM, and can mediate the destruction of pancreatic β cells, thus inducing the occurrence of type 1 diabetes." (PMID 36056051, 2022). "Similarly, IL-10-polarised islet-reactive CD4+ T cells were enriched in healthy donors and individuals with type 1 diabetes of later onset, who may be representative of T1DE2." (PMID 33084970, 2021). "Type 1 diabetes (T1D) is a multifactorial, organ/cell-specific disease resulting from an autoimmune destruction of insulin-producing β cells of the endocrine pancreas by CD4+ and CD8+ T cells, as well as macrophages infiltrating the islets." (PMID 31139178, 2019). "Therefore, it is possible that also in type 1 diabetes Tph cells could constitute a major subpopulation of CD4+ T cells at the level of inflamed islets." (PMID 31270583, 2019). "The review has shown evidence from one trial of normal volunteers that vitamin D3 supplementation may significantly increase Treg/CD4 ratios, and that vitamin D3 supplementation may increase Treg function, as demonstrated in a separate trial of type I diabetes patients." (PMID 31550254, 2019). "Type 1 diabetes mellitus (T1DM) is a CD4+ and CD8+ T-cell-dependent autoimmune disease that targets beta cell destruction, ultimately leading to hyperglycemia and insulin dependence." (PMID 29662071, 2018). "In autoimmune type 1 diabetes mellitus (T1D), auto-reactive clones of CD4+ and CD8+ T lymphocytes in the periphery evolve into pancreas-infiltrating T lymphocytes (PILs), which destroy insulin-producing beta-cells through inflammatory insulitis." (PMID 26606254, 2015). "Future studies will investigate whether DM-dependent peptide selection is required in the thymus for maturation of pathogenic CD4+ T cells and/or presentation of islet antigens for activation of autoreactive CD4+ T cells during the development of type 1 diabetes." (PMID 23418596, 2013). "Indeed, the addition of B7-H4.Ig protein inhibited the anti-CD3–induced proliferation of activated T cells from patients with type 1 diabetes (T1D), arresting CD4+ T cell cycle progression in G0/G1 phase and inducing apoptosis of both activated CD4+ and CD8+ T cells from these patients." (PMID 22238573, 2012). "In this study, although we focused our studies on CD4+ T cells, it is also important to study phenotypic and functional alterations of CD8+ T cells by the ATG therapy, given the pathogenic role of CD8+ T cells in type 1 diabetes, which will be addressed in the following future studies." (PMID 23237483, 2012). "The impact on Tfh cells was also studied in a model of type 1 diabetes, showing that Tfh and other ICOS+ CD4+ T cell subsets are the most sensitive to the effect of abatacept." (PMID 38567291, 2024).
type 1 diabetes (continued). "Promoted PNMA8A/PNMAL1 was listed among stroke candidate genes, as well as among cytotoxicity-related genes in CD4+ and CD8+ T cells that mark progression to type 1 diabetes." (PMID 38674024, 2024). "The percentages CD3+ T lymphocytes, CD19+ B lymphocytes, CD3+CD4+ and CD3+CD8+ T lymphocytes and NK cells in the patients with type 1 diabetes were analyzed in relation to the presence of anti-VCA antibodies in the IgM class." (PMID 36768715, 2023). "Along with that, by regulating T effector cells via the CD39/CD73 pathway and drastically reducing murine CD4+ T cell differentiation into Th1 or Th17, human GMSCs alleviated the diabetic condition in streptozotocin (STZ)-induced type 1 diabetes (T1DM) mice." (PMID 37626831, 2023). "The percentage of CD3+CD4+ T lymphocytes with the intracellular expression of IFN-γ+, IL-2, IL-4, IL-10 and IL-17 in the patients with type 1 diabetes and in the control group was analyzed." (PMID 36768715, 2023). "In addition to these factors, there are several common abnormalities of the immune system before the onset of type-1 diabetes, including the depletion of memory CD4+ cells and defective natural killer-cell activity, which could increase the ability of Toxoplasma gondii to infect a host." (PMID 36901457, 2023). "Type 1 diabetes (T1D) is a multifactorial autoimmune disorder in which autoreactive CD8+ and CD4+ T lymphocytes, together with B lymphocytes, infiltrate pancreatic islets of Langerhans, leading to the loss of insulin-producing β cells." (PMID 37731505, 2023). "We also observed clustering of response of type 1 diabetes samples using PCA of all responses, CD4+, CD8+ and IgG." (PMID 36207582, 2023). "On the other hand, a study focusing on the type 1 diabetes NOD mouse model, and assessing granzyme B and IFN-γ production as markers of CD8+ and CD4+ T-cell activation following MERTK inhibition with UNC2025 challenge, found incomplete penetrance." (PMID 37958886, 2023). "High numbers of CD4+ T cells and B cells predominate in NOD mice, while relatively small numbers of CD8+ T cells and macrophages were observed in patients with type 1 diabetes." (PMID 35242127, 2022). "We identified 79, 56 and 45 differentially methylated regions in CD4+ T cells, CD8+ T cells and CD4−CD8− cell fractions, respectively, between type 1 diabetes-specific autoantibody-positive individuals and control participants." (PMID 35142878, 2022). "Our study provides novel insights into the role of IL-10 in the modulation of neutrophils and CD4+ T cells in BDC2.5+ NOD mice, and suggests important crosstalk between gut microbiota and neutrophils in type 1 diabetes development." (PMID 34394099, 2021). "It is suggested that these “dual expressors” (DE) are increased in frequency in type 1 diabetes and that in people with type 1 diabetes there is a public BCR which can stimulate insulin-reactive CD4+ T cells." (PMID 34659258, 2021). "CD4+ T helper cells are a key player in the pathogenesis of Type 1 diabetes mellitus and have been consistently identified in the inflammatory infiltrate of islets from T1D patients." (PMID 33868170, 2021). "An increase was observed for the percentages of CD4+ Teff PD1+, CD4+ Teff PD1 low and CD4+ Teff PD1high cells of type 1 diabetes PBMC, post Pep3 administration, in respect to untreated cells." (PMID 31995625, 2020). "In EAE and type 1 diabetes, iNKT cells producing IFN-γ protect mice from developing the disease by dampening CD4+ T cell activation, including their production of IFN-γ and IL-1725,27,53." (PMID 29449556, 2018). "Islet specific CD4+ and CD8+ cells mediate diabetogenesis in NOD mice and have been identified in human type 1 diabetes patients." (PMID 26783747, 2016).